CRP (C-reactive protein)
Diseases named in the same sentence as CRP in open-access papers (continued):
Sharing a sentence is not in itself a finding about the gene and the disease.
Sepsis (continued). "In patients with severe sepsis, the NLR can better predict the occurrence of AKI than CRP and white blood cells." (PMID 36575502, 2022). "This systematic review was conducted to explore the role of CRP and PCT in the early detection of sepsis and in decision-making to start antibiotics or discharge patients." (PMID 36475186, 2022). "In the present study, we aimed to assess predictive accuracy of CRP, PCT, neutrophil CD64 index, in combination or alone, in predicting 28-day mortality in sepsis." (PMID 35907785, 2022). "In the late onset sepsis collective (6 LONS vs. 12 controls), cfDNA, DNase I, and CRP differed significantly compared to control group." (PMID 35053308, 2022). "The EOS group was significantly different from the non-sepsis group in 11 items including the both white blood cell (WBC) count and C-reactive protein (CRP) level of the mother before delivery (p < 0.05)." (PMID 35979478, 2022). "After the sepsis model was established using the CLP method, the serum contents of CORT, IL-6, TNF-α, CRP, and sICAM-1 in the model group were substantially increased compared to those of the control group." (PMID 36338128, 2022). "In the discovery cohort, mean values for the sequential organ failure assessment (SOFA) score as well as blood CRP and lactate on ICU admission were significantly higher in patients with sepsis than in SIRS patients." (PMID 35844509, 2022). "In the sepsis group, MDW value was 24.1 (median, IQR 21.6–28.1); AUC values for MDW, CRP, and PCT were 0.67 (95% CI, 0.64–0.69), 0.66 (95% CI, 0.63–0.68), and 0.75 (95% CI, 0.72–0.77), respectively." (PMID 36538555, 2022). "As rapid and reliable markers of inflammation, serum procalcitonin (PCT) and C-reactive protein (CRP) play irreplaceable roles in diagnosing infectious diseases and have a good clinical diagnosis and prognostic value for patients with sepsis and septic shock." (PMID 36177334, 2022). "The results of the single-predictor PDP showed that the IG% significantly increased the probability of sepsis, after the %TBSA and CRP." (PMID 34915849, 2021). "ROC curves were performed for PCT, CRP, and WBC levels to identify sepsis in the S group, and AUCs were calculated." (PMID 34344141, 2021). "We proposed a novel PCT-based score that performs better in detecting sepsis than serum PCT levels alone, C-reactive protein, and infection probability score." (PMID 33481913, 2021). "Compared with the sepsis group, PCT and hs-CRP levels, SOFA, MEDS, LODS, and APACHE-II scores, and early and late mortality rates were found to be significantly higher in the septic shock group." (PMID 34133658, 2021). "The present study investigated the incidence and onset of sepsis according to three different definitions as well as the accompanying time course of pro-inflammatory biomarkers (WBC, CRP, PCT, PSP) in a cohort of 90 severely burned patients over 14 days." (PMID 34442346, 2021). "We explored the potential of serial measurements of C-reactive protein (CRP), procalcitonin (PCT) and pancreatic stone protein (PSP) for the early recognition of sepsis in patients hospitalized in the intensive care unit (ICU)." (PMID 33879189, 2021). "In our study, high-sensitive CRP and sPLA2-IIA had better AUROCs followed by N%, PCT, and lactate in discriminating sepsis and differentiating BI." (PMID 34059757, 2021). "In severe sepsis, Antithrombin III, Protein C, C-reactive protein, Procalcitonin and Thrombopoietin had AUROCs 0.73–0.75." (PMID 33917002, 2021). "The development of nanosensors based on electrochemical, immunological, or magnetic principals provide highly sensitive, selective, and rapid detection of sepsis biomarkers such as PCT and CRP." (PMID 33803628, 2021).
Sepsis (continued). "Moreover, patients experiencing pneumonia and/or sepsis showed significantly increased serum kynurenine levels already five days prior to diagnosis and treatment initiation compared to the conventional marker C-reactive protein (CRP), which increased only immediately before the start of therapy." (PMID 33671985, 2021). "SD, standard deviation; BMI, body mass index; CWIC, Charlson weighted index of comorbidity; qSOFA, quick sepsis-related organ failure assessment; WBC, white blood count; CRP, C-reactive protein; IQR, interquartile range." (PMID 36168478, 2021). "The predictive ability to identify children who progressed to sepsis was significantly moderate for PCT (AUC 0.82), D-dimer (AUC 0.80), CRP (AUC 0.80), and IL-6 (AUC 0.74) and was significantly mild for N% (AUC 0.68) and HBP (AUC 0.67)." (PMID 34778149, 2021). "To date, numerous biomarkers such as interleukin-6 (IL-6), C-reactive protein (CRP), and procalcitonin (PCT), have been used for the early detection of sepsis." (PMID 34442376, 2021). "Cytokine levels had a significant predictive value only in the group of patients with uncomplicated sepsis, while levels of CRP, PCT and TPO were predictive only in the group of patients with severe sepsis." (PMID 33917002, 2021). "All biomarker values increased for several days before the clinical diagnosis of sepsis (PSP, 5 days; PCT, 3 days; CRP, 2 days)." (PMID 33879189, 2021). "Additional statistical comparison between the controls and documented sepsis patients was performed, and it was evident that nCD11b MFI, hs-CRP, PLT, Hb, and ALC showed significant differences between both groups." (PMID 34691286, 2021). "Conventional biomarkers such as white blood count (WBC), C-reactive protein (CRP), procalcitonin (PCT), and lactate have low prognostic value in predicting mortality in patients with CAP or sepsis." (PMID 34221750, 2021). "The AUC values for MDW, CRP, PCT, and white blood cells for predicting sepsis were 0.71 (95% confidence interval [CI], 0.67–0.75), 0.75 (95% CI, 0.71–0.78], 0.76 (95% CI, 0.72–0.79, and 0.61 (95% CI, 0.57–0.65), respectively." (PMID 33857210, 2021). "It demonstrates a slower rise than CRP and has been suggested to be inferior to PCT, CRP and WBC count in the diagnosis and prognosis of sepsis using the SEPSIS-3 criteria." (PMID 34720754, 2021). "The performance of MDW for sepsis detection was compared to that of procalcitonin (PCT) and C-reactive protein (CRP)." (PMID 34193208, 2021). "Even if CRP and PCT are commonly used in the context of the diagnosis of sepsis, both have shown suboptimal performance." (PMID 33879189, 2021). "The objective was to evaluate the performance of MDW for the detection of sepsis in the emergency department (ED) and to compare to procalcitonin (PCT) and C-reactive protein (CRP)." (PMID 34193208, 2021). "Currently, procalcitonin (PCT), interleukin-6 (IL-6), heparin-binding protein (HBP), C-reactive protein (CRP), serum resistin, and other indicators can be used to assess the severity and prognosis of sepsis." (PMID 34514164, 2021). "All five studies compared PCT to CRP and showed PCT has higher sensitivity and accuracy in diagnosing sepsis." (PMID 34912626, 2021). "The value of the Lac/Alb ratio, Lac/Alb × age score, CRP, Lac, SOFA score, and SAPS II to predict prognosis in patients with sepsis was analyzed." (PMID 34722573, 2021). "We aimed to assess the accuracy of C-Reactive Protein (CRP), protein carbonyls (PCO) and paraoxonase-1 (PON1) in differentiating dogs with sepsis from those with sterile inflammation and healthy ones, and predict the outcome in septic dogs." (PMID 34072427, 2021). "The levels of Hb and PA in sepsis group were lower than those in healthy control group (P < 0.05), while WBC, PLT, CRP, SAA and LDH levels in sepsis group were higher than those in healthy control group." (PMID 33981650, 2021).
Sepsis (continued). "In terms of laboratory tests, the biomarkers WBC, NLR, PLR, CRP, and MDW were all found to be significant predictors of sepsis." (PMID 34442376, 2021). "Current markers of sepsis including WBC, CRP, procalcitonin (PCT) or HLA-DR are insufficient for this purpose." (PMID 33828550, 2021). "For the diagnosis of sepsis, NLR at cutoff >1.7 had a sensitivity and specificity of 68.3% and 46.2%, respectively; CRP at cutoff >6 mg/dl had sensitivity and specificity of 78.05% and 92.31%, respectively." (PMID 33643735, 2021). "Because HBP levels increase prior to other known biomarkers (e.g., C-reactive protein (CRP), procalcitonin, white blood cell count (WBC) and lactate), it has emerged as a promising early predictor of severe sepsis with organ dysfunction." (PMID 34454419, 2021). "However, CRP was found not to be independently associated with sepsis." (PMID 34065206, 2021). "Several studies have compared PCT to CRP in the diagnosis of sepsis, and most of the evidence suggests that PCT is superior to CRP." (PMID 33654698, 2021). "High-sensitive CRP, sPLA2-IIA, and N% have the highest AUROC among all for both sepsis and BI detection in ED." (PMID 34059757, 2021). "IL-6 usually increases earlier than that of CRP and PCT, making it a potential biomarker for early detection of sepsis." (PMID 34630395, 2021). "The Scr, Albumin, WBC, CRP and PCT levels in sepsis patients were significantly different from those in healthy controls (P < 0.001)." (PMID 34376255, 2021). "Among the different serum markers of systemic inflammation and sepsis measured, we observed a higher value of the NLR and hs-CRP in Very Elderly compared to Elderly." (PMID 33451296, 2021). "ROC curve for diagnosing sepsis on the fifth day indicated an AUC of 0.837 for PCT (vs. 0.817, 0.811, and 0.802 for presepsin, CRP, and WBC, respectively)." (PMID 34641833, 2021). "Both, MVHSstatic and MVHSdynamic correlated moderate-to-strong with SOFA score, number of dysfunctional organs, lactate, CRP, IL-6 and PCT (all p < 0.001) in a pooled analysis that included healthy controls and sepsis patients." (PMID 33741036, 2021). "Laboratory findings, especially inflammatory markers such as C-reactive protein (CRP) and procalcitonin (PCT), help in diagnosing and monitoring sepsis prognosis." (PMID 33578598, 2021). "miR-122 showed higher AUC in comparison with CRP and TLC which had 66.6% sensitivity, 50% specificity, and 56.0% accuracy as a prognostic biomarker for sepsis." (PMID 34956235, 2021). "When compared to CRP, SAA levels rise more rapidly, peak on day 3 of sepsis, and return to baseline levels after four days." (PMID 34522543, 2021). "Generally, among the various indicators for diagnosing infection in patients with sepsis, PCT has a high specificity, but the sensitivity is average, while CRP has a high sensitivity but low specificity." (PMID 34233608, 2021). "The area under the ROC curve at the time of clinical sepsis was similar for all markers (PSP, 0.75; CRP, 0.77; PCT, 0.75)." (PMID 33879189, 2021). "Inflammatory markers including white blood count (WBC), CRP, and PCT were lower in ICU controls compared to sepsis patients." (PMID 34578983, 2021). "Although C-reactive protein (CRP) is a traditional biomarker that is elevated in inflammatory states, it has low specificity for diagnosing sepsis." (PMID 33926067, 2021). "CRP, PCT, and TPO levels were significantly higher in patients who deteriorated than in those who improved only in the group of patients with severe sepsis with sufficient predictive value." (PMID 33917002, 2021). "The multivariate regression analysis showed that under the premise of excluding confounding factors, PCT, CRP, NLR, PLR, and CRP*PCT were all independent prognostic factors of sepsis." (PMID 34233608, 2021). "CI, confidence interval; qSOFA, quick sepsis-related organ failure assessment; CRP, C-reactive protein." (PMID 36168478, 2021).
Sepsis (continued). "Evidence suggests that C-reactive protein (CRP), procalcitonin (PCT), and immune cells can predict sepsis severity in adult patients." (PMID 34233608, 2021). "It has been shown that a higher CRP/ALB ratio is an independent prognostic factor in conditions as diverse as chronic kidney disease, lung cancer and severe sepsis." (PMID 33779823, 2021). "The levels of Scr, CRP and WBC were increased but the level of albumin was decreased in sepsis patients relative to healthy controls (P < 0.001)." (PMID 34126975, 2021). "The levels of sIL-2R in the sepsis group were positively correlated with WBC, CRP, SAA, IL-6, and APACHE II (r = 0.387, p = 0.001; r = 0.248, p = 0.038; r = 0.402, p = 0.001; r = 0.532, p < 0.001; and r = 0.244, p = 0.042, respectively)." (PMID 34745113, 2021). "Similar studies have determined that a combination of markers such as CD64, c-reactive protein (CRP) and procalcitonin (PCT) have profound prognostic value, which can accurately discriminate sepsis in critically ill patients." (PMID 34356636, 2021). "Protein biomarkers demonstrate high specificity and sensitivity and include C-reactive protein (CRP) and Procalcitonin (PCT), which are the most commonly used protein biomarkers for the diagnosis of sepsis and monitoring of antibiotic therapy." (PMID 33766096, 2021). "Ultimately, evaluation of CRP and PON1 at admission seems a reliable support to diagnose sepsis and predict outcomes." (PMID 34072427, 2021). "Biomarkers, including lactate, C-reactive protein (CRP), and others, play an important role in diagnosing sepsis and guiding its management." (PMID 34439240, 2021). "The association of clinical sepsis diagnoses with the trajectories of PSP, CRP, and PCT in the 3 days preceding these diagnoses of sepsis were tested for markers of early sepsis detection." (PMID 33879189, 2021). "Several biomarkers (e.g., CRP, procalcitonin, WBC and differential counts, lactate, and interleukin-6) had already been investigated for their role of sepsis-related fatality." (PMID 34829326, 2021). "The results of our study revealed that diagnosis of the presumptive sepsis patients were made on the basis of physician’s judgment and laboratory investigations (CBC and CRP)." (PMID 33439876, 2021). "Monocyte distribution width (MDW) has been suggested as an early biomarker of sepsis, but few studies have compared MDW with conventional biomarkers, including C-reactive protein (CRP) and procalcitonin (PCT)." (PMID 33857210, 2021). "Univariate analysis results showed that ferritin, CRP, PLT, PCT, MPV, and the reciprocal form of MPR—PMR can be effective in distinguishing AOSD from sepsis." (PMID 33886787, 2021). "PSP started to increase 5 days before the clinical diagnosis of sepsis, PCT 3 and CRP 2 days, respectively." (PMID 33879189, 2021). "PSEP, C-reactive protein (CRP), and procalcitonin (PCT) were assessed at the onset of sepsis suspicion (T0), every 12–24 h for the first 48 h (T1–T4), and at the end of antibiotic therapy (T5)." (PMID 34068959, 2021). "Highly sensitive CRP (hs-CRP), complete blood count (CBC), blood culture, and nCD11b and mCD14 evaluations were all part of the laboratory sepsis evaluation (done by flow cytometry technology)." (PMID 34691286, 2021). "Other studies revealed that NLR has comparable or superior performance compared with C-reactive protein (CRP), but is frequently inferior to procalcitonin regarding sepsis or septic shock." (PMID 35052755, 2021). "The scores for WBC, CRP, SAA, IL-6, APACHE II, and SOFA in the sepsis group were all higher than those in the infection group, with statistical significance (p < 0.05)." (PMID 34745113, 2021). "In conclusion, these results confirm that oxidation is present during inflammatory conditions and especially in sepsis and support the role of CRP and PON1 in confirming a clinical diagnosis of sepsis." (PMID 34072427, 2021).
Sepsis (continued). "Various biomarkers, including C-reactive protein (CRP), procalcitonin (PCT), neutrophil CD64, interleukin-8, and interleukin-27, are used for sepsis diagnosis." (PMID 34095300, 2021). "The objective of our study is to assess the prognostic value of routinely used severity scores (SOFA and APACHE-II) and biochemical markers (CRP and PCT) between admission and the second day of admission in ICU patients with sepsis and septic shock." (PMID 34430091, 2021). "Reportedly, PCT, CRP, lactate levels, and SOFA scores have a moderate predictive value in sepsis prognosis, while prognosis accuracy depends much on multiple assessments and measurements throughout disease progression." (PMID 34326834, 2021). "In the present study, we evaluated the potential predictive role of IFN-γ and IL-5 in cord and venous blood, together with the determination of C-reactive protein and procalcitonin (PCT) for sepsis development in premature neonates." (PMID 33521320, 2021). "In conclusion, the present study first evaluated the correlation between CRP/Alb and PCT/Alb levels and the mortality of sepsis-induced AKI patients." (PMID 34141715, 2021). "High-sensitive CRP, PCT, and sPLA2-IIA had higher cut-off points in BI detection than in sepsis detection." (PMID 34059757, 2021). "Circulating resistin has been positively correlated with C-reactive protein (CRP), TNF-α, and IL-6 in type 2 diabetes, rheumatoid arthritis, chronic kidney disease, sepsis, and coronary atherosclerosis." (PMID 34639186, 2021). "White blood cells (leukocytes, WBC), plasma C-reactive protein (CRP), and procalcitonin (PCT) are listed as inflammatory variables in the International Guidelines for Management of Severe Sepsis and Septic Shock: 2012 (Surviving Sepsis Campaign)." (PMID 33505219, 2021). "Then, PSEP, CRP and PCT were benchmarked for their ability to discriminate neonates with severe clinical courses (sepsis and septic shock) from those with a milder course (infection) after the onset of symptoms." (PMID 34068959, 2021). "Corresponding to the detected correlation of CRP in saliva and serum samples of neonates undergoing sepsis, both in vitro models of the BSB showed an elevated transport of CRP in the direction of saliva." (PMID 33673378, 2021). "Pretreatment of rats with cefazolin resulted in a significant reduction in the serum levels of TNF-α, CRP, and TREM as compared with the rats from the sepsis group (p < 0.05)." (PMID 32348434, 2020). "IL-6 and TNF-α concurrently stimulate the production of C-reactive protein (CRP) and procalcitonin (PCT), which are the most widely used inflammatory biomarkers in patients with sepsis in clinical practice." (PMID 32778146, 2020). "In our study, the levels of WBC, CRP, and PCT in KD patients were increased but lower than the levels of sepsis patients, indicating that the immune-pathogenesis of KD lies somewhere between sepsis and viral infection." (PMID 32792679, 2020). "According to the K–S test results, data of WBC (P = 0.079), CRP (P = 0.065), and SOFA score (P = 0.200) in sepsis group were consistent with the normal distribution, and other data (all P < 0.05) were non-normal distributional." (PMID 32188465, 2020). "Further, the rats treated with cefazolin and etanercept demonstrated significantly reduced levels of serum TNF-α, CRP, TREM, and MDA as compared with those from the sepsis group (p < 0.05)." (PMID 32348434, 2020). "This 4-variable model that incorporates clinical admission, diagnosis of sepsis, SAPS II and basal serum CRP easily identifies the 3 ABD phenotypes." (PMID 32358385, 2020). "Sepsis patients had a significantly higher SOFA score and higher CRP and PCT levels than infection patients at enrollment." (PMID 32214905, 2020). "Pretreatment of rats from sepsis + cefazolin group with cefazolin led to a significant reduction in the serum levels of CRP, TNF-α, and TREM as compared with rats from sepsis group." (PMID 32348434, 2020).